ADAM12 (ADAM metallopeptidase domain 12)
Diseases named in the same sentence as ADAM12 in open-access papers (continued):
Sharing a sentence is not in itself a finding about the gene and the disease.
ovarian carcinoma (6 papers, 2013 to 2022). A malignant neoplasm originating from the surface ovarian epithelium. "ADAM12 was also regarded as a new biomarker of ovarian cancer, because of its low expression levels in normal tissues and high expression levels in ovarian cancer tissues, and high expression levels were associated with a poor survival in aggressive ovarian cancer as well." (PMID 27557513, 2016). "ADAM12 was a tumor marker and has negative prognostic value for overall survival in ovarian cancer." (PMID 32315343, 2020).
esophageal cancer (5 papers, 2016 to 2023). A primary or metastatic malignant neoplasm involving the esophagus. "We take this to imply that ADAM12 is a purely stromal activation marker, as also shown for pancreatic and esophageal cancer." (PMID 35413826, 2022). "In addition, effective activation of the positive feedback loop composed of ADAM12 and focal adhesion kinase enhances the interaction between tumor cells and the extracellular matrix, thus promoting the metastasis of esophageal cancer." (PMID 34604068, 2021). "In addition, the analysis of gene expression profiles of patients with esophageal cancer identified ADAM12 as a noninflammatory-related serum marker for IL-6-producing CAFs, and serum levels of ADAM12 predicted unfavorable responses to neoadjuvant chemoradiation." (PMID 36572816, 2023).
knee osteoarthritis (5 papers, 2013 to 2017). "Previous studies that evaluated the association between a disintegrin and metalloprotease 12 (ADAM12) gene polymorphisms and knee osteoarthritis (KOA) have given controversial and indefinite results." (PMID 29100419, 2017). "ADAM12 polymorphisms may be associated with the risk of knee osteoarthritis (KOA), but currently available evidence remains controversial." (PMID 28929114, 2017). "Although several studies have suggested that ADAM12 SNPs can influence the susceptibility to knee osteoarthritis but no consensus have been achieved." (PMID 28929114, 2017).
liver fibrosis (5 papers, 2009 to 2024). "In keeping with our results, metallopeptidase ADAM12 has also been reported to be upregulated in glaucomatous lamina cibrosa cells and is also associated with liver-fibrosis." (PMID 38990974, 2024). "A previous research implied that RACK1 associated with ADAM12 and promoted its translocation to membrane in PKC-dependent manner in HSCs, suggesting that RACK1 might contribute to the development of liver fibrosis." (PMID 23555900, 2013). "In this work, confronting differential models with qualitative biological observations, we obtained predictions giving new insights into the role of ADAM12 in TGF-β signaling and hepatic fibrosis process." (PMID 19778441, 2009). "ADAM12 is up-regulated during chronic liver injury and modulates TGF-β activity, thereby contributing to TGF-β dependent liver fibrosis." (PMID 19778441, 2009). "Since RACK1 has been reported to be involved in the regulation of cellular apoptosis and ADAM12 translation, it is likely that the up-regulation of RACK1 induced by TGF-β1 may contribute to liver fibrosis on other aspects." (PMID 23555900, 2013). "In our case, ADAM12, which according to our predictions modifies TGF-β signaling, could be partly responsible for the changes observed in TGF-β signaling during liver fibrosis." (PMID 19778441, 2009). "Therefore, the expression of the ADAM12 gene in the liver may promote the progression of hepatocellular carcinoma through the formation of liver fibrosis, but the data are not conclusive." (PMID 35459884, 2022).
osteoarthritis (5 papers, 2010 to 2024). A noninflammatory degenerative joint disease occurring chiefly in older persons, characterized by degeneration of the articular cartilage, hypertrophy of bone at the margins and changes in the synovial membrane. "Our subgroup analysis revealed an association between the ADAM12 polymorphism rs1871054 in Asians and osteoarthritis [C vs. T: OR = 1.61, 95% CI (1.25, 2.08), P < 0.001], albeit this was only for three studies." (PMID 36855121, 2023). "All case–control studies on ADAM12 rs3740199, rs1871054, rs1044122, and rs1278279 polymorphisms and osteoarthritis were searched." (PMID 36855121, 2023). "Polymorphism at the rs1871054 site of ADAM12 is associated with genetic susceptibility to osteoarthritis, but rs3740199, rs1044122, and rs1278279 site polymorphisms are not." (PMID 36855121, 2023). "There have been many studies on the correlation between ADAM12 polymorphisms and genetic susceptibility to osteoarthritis, but the results remain inconclusive." (PMID 36855121, 2023). "Meta-analysis showed that the rs1871054 polymorphism of ADAM12 was associated with osteoarthritis in dominant, recessive, allelic, and homozygote genetic models [C vs. T: OR = 1.34 95% CI (1.05, 1.71), P < 0.001]." (PMID 36855121, 2023). "In summary, we have identified that the rs1871054 variant within the ADAM12 gene is a risk factor for increased osteoarthritis susceptibility and severity." (PMID 25667922, 2015). "The ADAM12 is also implicated in the pathogenesis of osteoarthritis." (PMID 27545300, 2016). "In addition, the ADAM12 polymorphism rs1871054 is associated with osteoarthritis in patients younger than 60 years of age [C vs. T: OR = 1.39, 95% CI (1.01, 1.92), P = 0.289]; however, the ADAM12 gene rs3740199, rs1044122, and rs1278279 site polymorphisms were not significantly." (PMID 36855121, 2023). "Importantly, ADAM12 has been reported be highly expressed by the chondrocytes of osteoarthritis cartilage, a sizable proportion of which may be MPCs." (PMID 20167057, 2010). "For the 8 gene loci ESR1 rs2234693, CYP19A1 rs700518, ADAM12 rs3740199, ACE I/D rs4340, VDRrs731236, TGF-β rs1982073, FAS rs1800682, ADAMTS5 rs226794, the cumulative sample sizes were deemed sufficient to conclude that they are not correlated with osteoarthritis." (PMID 39248710, 2024).
small cell lung carcinoma (5 papers, 2014 to 2022). Small cell lung cancer (SCLC) is a highly aggressive malignant neoplasm, accounting for 10-15% of lung cancer cases, characterized byrapid growth, and early metastasis. "It was also shown that E2F transcription factor 1 (E2F1) drives ADAM12 expression in small cell lung cancer cells." (PMID 35610640, 2022). "Among the three identified TME-based prognostic genes (LPPR4, ADAM12, NOX4), ADAM12, which was found to be overexpressed in small cell lung cancer patients, has been proven to be a potential prognostic biomarker for cancer." (PMID 35178071, 2021). "Other study reported that ADAM12 was highly expressed in small cell lung cancer (SCLC) and could be an effective marker for diagnosis and prognosis." (PMID 27557513, 2016).
triple-negative breast carcinoma (5 papers, 2015 to 2024). An invasive breast carcinoma which is negative for expression of estrogen receptor (ER), progesterone receptor (PR), and human epidermal growth factor receptor 2 (HER2). "The effect of miRNA30b on triple-negative breast cancer would be achieved partly at least through inhibiting the expression of ADAM12." (PMID 39742357, 2024). "After establishing that TAK1 mediates ADAM12 induction by TGF-β in normal human cells, we asked whether it was also involved in the sustained expression of ADAM12 seen in tumor cells, and particularly in Triple-Negative Breast Cancer (TNBC) cells." (PMID 30753595, 2019). "The oncogenic role of ADAM12 is especially clear in the case of Triple-Negative Breast Cancer." (PMID 30753595, 2019).
Down syndrome (4 papers, 2009 to 2022). "ADAM12 gene expression has also been linked to human intelligence through a genome-wide association study (GWAS) and the expressed protein serves as a maternal marker for Down’s syndrome; this evidence suggests an association with neural function." (PMID 33941233, 2021). "Interestingly, ADAM12 is a known biomarker for Down syndrome, demonstrating the applicability of this family to biochemical assays for diagnosis." (PMID 19156209, 2009). "Moreover, we found differentially methylated probes within ITGA9 and ADAM12 genes, whose methylation is altered in systemic sclerosis, and within the PRDM8 gene, whose methylation is affected in dyskeratosis congenita and Down syndrome." (PMID 28861129, 2017).
hepatocellular carcinoma (4 papers, 2006 to 2023). A malignant tumor that arises from hepatocytes. "The expression of ADAM12 may be associated with immune cell infiltration in hepatocellular carcinoma; these invading cells include macrophages, immature dendritic cells, follicular T cells, and helper T cells." (PMID 35459884, 2022). "ADAM12 is significantly more expressed in hepatocellular carcinoma (HCC) tissues than in surrounding tissues, and a signal pathway related to ADAM12 is found." (PMID 36843929, 2023). "The clinical data used to characterize 374 patients with hepatocellular carcinoma were downloaded from the TCGA database and divided into high and low groups based on the median ADAM12 gene expression level." (PMID 35459884, 2022). "The expression of the ADAM12 gene in hepatocellular carcinoma was significantly correlated with T stage (p = 0.01), age (p = 0.03), sex (p = 0.02), pathological stage (p = 7.2e−03), and histological grade (p = 0.01)." (PMID 35459884, 2022). "In hepatocellular carcinoma, the expression of the ADAM12 gene in tumour tissues was significantly higher than that in normal tissues (p = 6.4e−06)." (PMID 35459884, 2022). "The Wilcoxon signed-rank test and logistic regression analysis were performed to evaluate the relationship between ADAM12 gene expression and clinicopathological variables in patients with hepatocellular carcinoma." (PMID 35459884, 2022). "In conclusion, we used bioinformatics to explore the close correlation between high ADAM12 gene expression and hepatocellular carcinoma." (PMID 35459884, 2022). "On the basis of The Cancer Genome Atlas (TCGA) datasets, in this study, the relationship between ADAM12 gene expression and hepatocellular carcinoma (HCC), the prognostic value of this relationship, and the potential mechanisms influencing HCC development were evaluated." (PMID 35459884, 2022).
keloid (4 papers, 2016 to 2021). An irregularly shaped, elevated mark on the skin caused by deposits of excessive amounts of collagen during wound healing. "These lncRNAs were associated with the related genes of keloid (ADAM12, COL6A3, and EGF)." (PMID 28101509, 2016). "IF staining results showed that the proportion of ADAM12+/NREP+ cells was higher in keloids than in normal control." (PMID 34140509, 2021). "The immunofluorescence experiments showed similar results that only part of ADAM12 positive mesenchymal fibroblasts were α-SMA positive in keloid." (PMID 34140509, 2021). "We also analyzed the expression of ADAM12 and α-SMA (encoded by ACTA2) in keloid and normal scar tissues by immunofluorescence." (PMID 34140509, 2021). "It was reported that up‐regulated ADAM12 in the central part of keloids may be involved in processes leading to clinical regression." (PMID 33932142, 2021). "The top 50 DEGs in lesional versus normal skin comparison included products related to fibrosis and cartilage/bone-differentiation (ADAM12, ASPN, COL10A1, COL11A1, FBN2), previously reported to be dysregulated in keloids." (PMID 33329590, 2020). "ADAM12 are reluctant to adhere to fibronectin, a key ECM protein in keloids." (PMID 28101509, 2016).
pancreatic ductal adenocarcinoma (4 papers, 2022 to 2024). An infiltrating adenocarcinoma that arises from the epithelial cells of the pancreas. "ADAM12, a disintegrin and metalloprotease, is expressed in cancer-associated fibroblasts (CAFs) and tumor cells in pancreatic ductal adenocarcinoma (PDAC)." (PMID 39478152, 2024). "We further analyzed ADAM12 expression in publicly available datasets from cohorts of patients with skin cutaneous melanoma, pancreatic ductal adenocarcinoma, prostate adenocarcinoma or colon adenocarcinoma." (PMID 37798557, 2023). "Therefore, we set out to test the impact of prophylactic and therapeutic vaccination against ADAM12 on tumor desmoplasia in preclinical models of pancreatic ductal adenocarcinoma." (PMID 39478152, 2024).
Alzheimer disease (3 papers, 2021 to 2024). A progressive, neurodegenerative disease characterized by loss of function and death of nerve cells in several areas of the brain leading to loss of cognitive function such as memory and language. "Genetic variants in ADAM12 have been associated with neurological diseases such as multiple sclerosis and Alzheimer’s disease." (PMID 37935791, 2024). "Altered expression of ADAM12 is implicated in a variety of pathological diseases, such as diabetes, sepsis, rheumatoid arthritis, Alzheimer’s disease, atherosclerosis, cardiovascular disease, asthma, and cancer." (PMID 33923541, 2021). "In the human brain, ADAM12 is involved in the pathophysiology of several disorders, such as brain cancer, stroke, Alzheimer’s disease, and experimental autoimmune encephalomyelitis." (PMID 36498866, 2022).
asthma (3 papers, 2015 to 2021). "Neither ADAM33 antibody cross-reacted with recombinant ADAM8 and ADAM12, which have been associated with asthma and show high homology with ADAM33." (PMID 27489884, 2016).
endometriosis (3 papers, 2015 to 2023). The growth of functional endometrial tissue in anatomic sites outside the uterine body. "In a model of the invasive disease endometriosis, we identified A Disintegrin and Metalloproteinase 12 (ADAM12) as a protease implicated in HB-EGF shedding." (PMID 26477568, 2015). "Therefore we performed a correlative multivariate analysis to identify the primary ADAM protease responsible for HB-EGF shedding in endometriosis, and found ADAM12 to be most associated." (PMID 26477568, 2015). "We found that ADAM12 activity correlated closely with HB-EGF shedding in endometriosis; therefore, we developed a specific inhibitor of ADAM12 based on its recombinant prodomain (PA12) to reduce HB-EGF shedding, and demonstrated it as effective." (PMID 26477568, 2015). "Future work is needed to understand the functional implications of ADAM12 inhibition in animal models of endometriosis along with other models of disease, and PA12 represents a promising tool for that aim." (PMID 26477568, 2015). "qRT-PCR was carried out using the total RNA that was extracted from 10 pairs of normal endometrium and EM tissues and showed higher expressions of BIN2, CCR5, and MRC1 and lower expressions of SYK and ADAM12 in endometriosis tissue than in non-endometriosis tissue." (PMID 34295919, 2021). "Thus, the computational CSR analysis here provides evidence that ADAM12 mediates HB-EGF shedding in endometriosis, and therefore represents a promising avenue of investigation." (PMID 26477568, 2015). "We found that ADAM12 inhibition via both PA12 treatment and genetic knockdown decreased HB-EGF shedding in endometriosis cell culture, while additionally reducing cell migration." (PMID 26477568, 2015). "Here we report recombinant PA12 as a specific inhibitor of ADAM12 with sub-micromolar potency, and demonstrate its application to reduce HB-EGF shedding and cellular migration in endometriosis cell culture." (PMID 26477568, 2015).
experimental autoimmune encephalomyelitis (3 papers, 2015 to 2022). An autoimmune demyelinating disease of the central nervous system that is produced experimentally in animals by the injection of homogenized brain or spinal cord in Freund's adjuvant. "We found that genetic loss of ADAM12 profoundly alleviated Th1-mediated neuroinflammation and thus disease severity in experimental autoimmune encephalomyelitis, a model of multiple sclerosis." (PMID 32572163, 2021). "Related to the neural vascular barrier, ADAM12 expressed in T cells was suggested to potentiate the transmigration of T cells through vascular barrier in the experimental autoimmune encephalomyelitis mice." (PMID 26242473, 2015).
melanoma (3 papers, 2013 to 2024). A malignant, usually aggressive tumor composed of atypical, neoplastic melanocytes. "A recent study revealed the presence of a unique type of MSCs (known as slow-cycling ADAM12+PDGFRα+ MSCs) at tumor edges in melanoma, pancreatic cancer, and prostate cancer mouse models." (PMID 38779660, 2024). "Genetic depletion of ADAM12+ cells normalizes the tumor vasculature and decreases hypoxia and acidity, restoring antitumor immunity and blocking tumor growth in mouse models of melanoma and neuroendocrine pancreatic cancer." (PMID 37798557, 2023). "In addition, in various solid tumors, such as melanoma, a population of slow-cycling ADAM12+PDGFRα+ MSCs exists." (PMID 38779660, 2024). "After inoculating MO5 tumor cells in ADAM12-tTA-CreYFP mice (maintained on doxycycline until tumor injection), we observed that yellow fluorescent protein (YFP)+ cells (progeny of ADAM12+ cells) constituted about 1% of stromal cells in advanced melanomas." (PMID 37798557, 2023). "As observed in the melanoma, PDPN+PDGFRα+ CAFs were reorganized but still present in similar numbers in tumors lacking ADAM12+ MSCs, and the vasculature displayed increased pericyte coverage and ICAM1 expression." (PMID 37798557, 2023).
metastatic disease (3 papers, 2014 to 2025). "ADAM12 is linked to the induction of EphA2-dependent cell migration in metastatic tumors." (PMID 33946495, 2021). "ADAM12, ephrin-A1, and EphA2-contribute to growth or cell migration in primary and metastatic tumors." (PMID 33946495, 2021). "The upregulation of genes encoding matrix associated factors including proteases and cell adhesion molecules such as ADAM12, NTN3, LRRC15, CDH17, PCDH19, VTN highlighted the relevance of the tumor microenvironment and cell–cell and cell–matrix interaction for progression to metastatic disease." (PMID 41402347, 2025).
Miscarriage (3 papers, 2014 to 2023). A pregnancy that ends at a stage in which the fetus is incapable of surviving on its own, defined as the spontaneous loss of a fetus before the 22th week of pregnancy. "ADAM12 can diagnose ectopic pregnancy and spontaneous abortion before the ultrasonographic detection of the conditions, and can be used as dynamic monitoring of early pregnancy, If adding progesterone and human chorionic gonadotropin comprehensive judgment detection rate is higher." (PMID 24830297, 2014). "ADAM12 is a promising marker for the diagnosis of complete spontaneous abortion and ectopic pregnancy in symptomatic women, and under certain conditions, ADAM12 can diagnose ectopic pregnancy and spontaneous abortion before an ultrasonographic detection of the conditions." (PMID 24830297, 2014).
multiple sclerosis (3 papers, 2013 to 2024). A progressive autoimmune disorder affecting the central nervous system resulting in demyelination. "It will be important to determine the levels of ADAM12 in T cells in pathologies where Th17 cells are implicated, such as multiple sclerosis patients, psoriasis and other inflammatory disorders." (PMID 24363794, 2013).
Peripheral Artery Disease (3 papers, 2021 to 2025). "In mice, ADAM12 has been identified as an important gene associated with modifications of peripheral artery disease severity." (PMID 37662558, 2023).
pituitary adenoma (3 papers, 2019 to 2021). "Furthermore, ADAM12 overexpression is associated with tumor invasion in pituitary adenoma via the EGFR/ERK signaling pathway." (PMID 31796052, 2019). "Interestingly, subsequent studies also indicated that ADAM12 induced EMT in pituitary adenomas through the EGFR/ERK signaling pathway and promoted cell migration, invasion, and proliferation." (PMID 34604068, 2021). "ADAM12 and MMP14 are significantly correlated with cavernous sinus invasion in patients with pituitary adenomas." (PMID 34604068, 2021).
thyroid cancer (3 papers, 2021 to 2023). "Another study revealed that LINC00284 might promote the progression of thyroid cancer by competitively binding to miR-30d-5p and thus activating ADAM12-dependent Notch signaling pathway." (PMID 36530988, 2022).